VIM (vimentin)
Diseases named in the same sentence as VIM in open-access papers (continued):
Sharing a sentence is not in itself a finding about the gene and the disease.
cancer (continued). "We observed upregulated epithelial marker E-cadherin in BORA knockdown cells and downregulated N-cadherin, Vimentin and other proteins associated with EMT pathway, which has been verified to play a critical role in migration and invasion of cancer cells." (PMID 32655322, 2020). "Currently, studies in malignant tumors have shown that vimentin plays an important role in cell cycle regulation, migration, adhesion, and EMT of carcinoma." (PMID 32850341, 2020). "Accumulating evidence suggest that EMT induction is one of the most important mechanisms for cancer metastasis, and the down-regulation of epithelial marker E-cadherin and the upregulation of mesenchymal marker vimentin are typical characteristics of EMT." (PMID 31931851, 2020). "Its decreased expression represents upregulated cancer invasion ability and poor prognosis, causing EMT progression together with increased expression of vimentin, a mesenchymal cell marker." (PMID 33255835, 2020). "Increased expression of vimentin, an intermediate filament protein that is associated with a migratory phenotype, is also used as an EMT marker in cancer." (PMID 32325994, 2020). "After activation of autophagy, the migration of cancer cells is upregulated, and the cancer cells are able to acquire EMT (enhanced levels of vimentin)." (PMID 32503307, 2020). "On the other hand, the epithelial cancer cells express mesenchymal proteins such as vimentin and N- cadherin, and become mesenchymal cells, ready for migration." (PMID 33330053, 2020). "EpCAM+ and Vimentin+ aneuploid CTCs and CTECs, produced by the transdifferentiation of CSCs or heterotypic cell fusion of cancer cells with ECs, were detected in cancer patients with a variety of epithelial carcinomas." (PMID 32599893, 2020). "Here, vimentin collapsed to the perinuclear space and maintained strong anti-migratory and anti-invasive properties in cancer cells." (PMID 31940801, 2020). "Once cancer cells arrest the expression of epithelial markers including E-cadherin, the expression of mesenchymal markers such as N-cadherin and vimentin becomes upregulated." (PMID 33374849, 2020). "Altogether, our data demonstrate that EMT-related proteins, such as N-cadherin or vimentin are differentially expressed in HCC cancer cells depending on the proliferative rate under hypoxic conditions." (PMID 32001727, 2020). "Previous studies have shown that the invasiveness of cancer cells is highly reflected in the expression level of vimentin in the cells." (PMID 32365781, 2020). "The subcellular localization and organization of vimentin filaments were previously shown to be altered in cancers." (PMID 33400741, 2020). "The expression of Vimentin as a mesenchymal marker along with rising grade of cancer, pathological stages, and metastasis to regional lymph nodes increased furthermore, in cancers with vascular invasion, Vimentin value was high." (PMID 32665775, 2020). "It has been found that LAMB3 activates EMT mechanism through vimentin and Slug upregulation to reduce the CP efficacy in elimination of cancer cells." (PMID 32503307, 2020). "We found that genetic overexpression of PDCD10 (OE-PDCD10) increased cancer metastasis by down-regulating E-cad and enhancing Vimentin (VIM) thereby inducing EMT and promoting β-catenin/Wnt-mediated cell migration." (PMID 32483426, 2020). "The expression of cellular EMT marker changes, including MMP‐9, vimentin and E‐cadherin, has implications for the cancer invasion‐metastasis process." (PMID 32294802, 2020). "Accruing literatures have revealed that inhibition of epithelial markers (E‐cadherin and β‐catenin) as well as elevation of mesenchymal markers (Vimentin, N‐cadherin, Snail, and Slug) contributed to EMT, which was associated with development of cancers." (PMID 32862492, 2020). "The Akt/mTOR signaling pathway is typically abnormally activated in a variety of malignant tumors and causes abnormal expression of downstream genes such as PFKFB2, p21, Vimentin, and Bcl-2." (PMID 33282634, 2020).
cancer (continued). "We examined the expression of EMT‐associated markers and found that the E‐cadherin expression was significantly lower in cancer tissues than in para‐cancer tissues while the expression of vimentin, Snail and ZEB‐1 was notably increased in cancer tissues." (PMID 33128348, 2020). "TGF-β induces the upregulation mesenchymal markers such as vimentin and downregulation of the epithelial marker E-cadherin, which are considered critical prerequisites for metastasis in numerous human cancers." (PMID 32033410, 2020). "In the development of EMT, cancer cells lose the properties of epithelial cells and develop mesenchymal cell properties, including overexpression of vimentin." (PMID 32765634, 2020). "As EMT is crucial for cancer cell migration and invasion, in order to elucidate the role of the Shh/Gli1 pathway in the regulation of EMT in GC, the association between E-cad, VIM and Gli1 expression was investigated by immunohistochemistry in GC tissues." (PMID 32328197, 2020). "Western blot assays showed that the decreased CDH1 expression and enhanced mesenchymal (CDH2 and vimentin) and cancer stemness (CD44, ABCG2, OCT4 and MYC) marker expression were abolished after treating MCF-7OE-UBE2O cells with rapamycin." (PMID 31907353, 2020). "During the carcinogenesis, the involved tissues were demonstrated to acquire rigidity compared to the normal tissues, due to an increase of cellular vimentin expression and of cancer cell malignancy due to the re-organization of cell polarity." (PMID 32933173, 2020). "We actually showed that in SiHa cancer cells, chronic acidosis inversely influenced the expression of E-cadherin and vimentin, two critical markers of the epithelial and mesenchymal status, respectively." (PMID 31974393, 2020). "Vimentin expression was low in the first stage of cancer, while a significant increase was observed in the other stages up to stage four (P value˂0.05)." (PMID 32665775, 2020). "Vimentin is a potential cancer therapeutic target, since it is overexpressed in a number of cancers, and influences cell shape and motility in the process of EMT that occurs during metastasis." (PMID 31973707, 2020). "Transcriptional expressions of VIM were significantly elevated in cancer tissue compared with normal tissues, while expression of CDH1, a key epithelial marker, was significantly decreased in cancer tissue in multiple datasets." (PMID 31915310, 2020). "Probably the closest to a vimentin-specific anti-cancer drug is the recently discovered FOXC2-inhibiting vimentin effector 1 (FiVe1) compound." (PMID 31940801, 2020). "In summary, along with cancer progression level of Vimentin expression varies inversely with E-cadherin expression and by increasing metastasis and invasion the Vimentin expression elevates." (PMID 32665775, 2020). "Conversely, FOSL1 and VIM, which are ubiquitously expressed in normal mesenchymal cells and overexpressed in many cancers, had a more than 5- to 10-fold higher expression in CD44high/CD24−/low cells from triple-negative/basal-like cell lines." (PMID 32423137, 2020). "Accordingly, vimentin appears to be upregulated in drug-resistant cancer cells of a great variety of entities." (PMID 32466394, 2020). "The role of vimentin and phospho-paxillin as active players in cell focal adhesion and migration, as well as in pathological conditions, including cancer development and metastasis, is widely discussed in literature." (PMID 32664186, 2020). "IHC also showed positive staining for E-cadherin and Vimentin implying the presence of heterogeneous cell phenotypes in the miPS-Huh7cm cell-derived malignant tumours." (PMID 32203212, 2020). "Vimentin is currently used as an important marker protein for mesenchymal cells, and its positive or increased expression is considered to be an indicator of cancer cell invasion phenotype." (PMID 32580247, 2020).
cancer (continued). "In cancer cells, enhancement of vimentin solubility with cholesterol‐lowering statin drugs reduces malignant characteristics which associate with enhanced apoptosis." (PMID 32590878, 2020). "Specifically, lowered numbers of cells expressing E-cadherin and cytokeratin were detected among primary site cancer cells together with aberrant N-cadherin expression and a moderate number of cells immunolabeled for vimentin." (PMID 33297475, 2020). "Vimentin expression, loss of E-cadherin, enhanced migratory activity, ECM production, and invasiveness accompany the acquisition of mesenchymal features by cancer cells." (PMID 33143259, 2020). "In cancer progression, vimentin’s role as a scaffolding protein of the cytoskeleton and marker of EMT is just as important and its ability to interfere with and mediate certain signaling pathways has been extensively described." (PMID 32466394, 2020). "Therefore, our study not only illustrates a mechanism underlying abrogation of Vimentin degradation during active AKT-driven LAD progression but also provides a foundation for developing Vimentin stability as a diagnostic marker or a therapeutic target for anti-cancer strategy." (PMID 33046716, 2020). "High vimentin is a biomarker in the mesenchymal state of cancer cells, mediating cytoskeletal organization, and focal adhesion maturation." (PMID 33040485, 2020). "Our in vitro 3D culture studies supported our in vivo observations for HGF + c-MET inhibition on EMT, with cancer cells expressing a significant increase in E-cadherin and a significant decrease in vimentin in this treatment group." (PMID 32203220, 2020). "Taken independently, this finding holds tremendous potential for therapeutic approaches to target increased vimentin levels in cancer that induce EMT." (PMID 31997977, 2020). "Increased expression of TWIST1 and vimentin in cancer tissues, as well as a decreased expression of programmed cell death factor 4 (PDCD4), and E-cadherin expression is all linked with malignant tissue degree." (PMID 32268527, 2020). "Both treatments actually reverted the upregulation of the mesenchymal markers SNAIL1, ZEB1 as well as N-cadherin and vimentin in acidosis-adapted cancer cells." (PMID 31974393, 2020). "In the past years there have been several studies, discussed in the following text, promising the possibility to specifically target vimentin and, thus, potentially affect cancer progression." (PMID 31940801, 2020). "E2F4as knockdown in cancer tissues resulted in an increase in the expression of E-cadherin and a decrease in the expression of Vimentin, Wnt-5β and Slug mRNA levels." (PMID 33287341, 2020). "Our results showed a homogenous expression of Vimentin in all primary cancer cell lines, whereas a differential expression pattern of Nestin was noted." (PMID 32742192, 2020). "Compensatory effects, such as those linked to the actin cytoskeleton, should therefore be taken into consideration while designing vimentin-based anti-cancer strategies." (PMID 31940801, 2020). "Immunofluorescence staining for E-cadherin/vimentin demonstrated that the mesenchymal characteristics of cancer cells were significantly upregulated after treatment with CM, while a number of their epithelial characteristics were retained." (PMID 33204333, 2020). "Epithelial mesenchymal transition(EMT)induction is one of the most important mechanisms for cancer metastasis, the downregulation of epithelial marker E-cadherin and the upregulation of mesenchymal marker vimentin are typical characteristics of EMT." (PMID 31931851, 2020). "Taken together, we proved that miR-515-3p suppresses cancer invasion and metastasis by directly targeting vimentin and MMP3." (PMID 33243974, 2020). "ccRCC is a peculiar carcinoma, being one of the few carcinomas that normally express both cytokeratin and vimentin type intermediate filaments, the latter being a well-established marker of mesenchymal differentiation." (PMID 32245446, 2020).
cancer (continued). "Increased expression levels of CCL5 mRNA and protein were observed in prostate cancer tumor tissues than para-carcinoma tissues, accompanied by the decreased expression of E-cadherin and increased expression of Vimentin." (PMID 32300100, 2020). "EMC conditioned medium led to the induction of a hybrid epithelial-mesenchymal cancer cell phenotype, characterised by co-expression of vimentin and cytokeratins." (PMID 31297730, 2019). "During EMT and cancer metastasis, the levels of proteins such as N-cadherin, Zeb1, and vimentin significantly increase while the amount of E-cadherin decreases due to SNAI1-dependent transcriptional regulation." (PMID 30736337, 2019). "GH itself has been suggested to stimulate EMT: autocrine/paracrine GH or treatment with GH induces a complete EMT program and significantly up-regulates the classical mesenchymal markers such as N-cadherin and vimentin in some cancers." (PMID 30867568, 2019). "Although Vimentin function is widely studied in cancer metastasis, the molecular mechanisms by which the suppression of Vimentin ameliorates metastasis in aggressive cancer cells remain to be identified." (PMID 31862882, 2019). "Recently, studies performed in cancer cells showed that inhibition of Atoh8 resulted in the downregulation of E-cadherin and upregulation of Vimentin bestowing mesenchymal phenotype to the cells." (PMID 31159500, 2019). "Immunofluorescence staining also showed that compared with untreated cells, actinomycin V treatment significantly decreased intracellular N-cadherin and vimentin content while increased the E-cadherin content in cancer cells." (PMID 31137656, 2019). "In untreated cancer cells, N-cadherin and vimentin proteins level was higher as compared to E-cadherin, while the cells which received pre-treatment of CRAd showed opposite results." (PMID 31097752, 2019). "Upregulation of vimentin expression has been reported in various cancer cells, including CRC (Satelli and Li, 2011)." (PMID 31217787, 2019). "Higher expression of vimentin has also been correlated with chemoresistance in various cancer types." (PMID 31126068, 2019). "To check for the EMT or MET process in our cancer proliferation, we once again targeted Vimentin for fluorescence tracking in the culture with time." (PMID 30792889, 2019). "Vimentin expression is involved in acquisition of mesenchymal phenotype that induces cell migration, invasion and metastasis in cancer." (PMID 31027221, 2019). "Vimentin has been shown to interact with a variety of proteins such as GlcNAc, p62, and other molecules, to promote invasion in multiple malignant tumor types." (PMID 31761784, 2019). "The overexpression of vimentin in cancer cells promotes cellular proliferation, invasion and migration." (PMID 31137656, 2019). "EpCAM and vimentin expression levels of biological replicates from the mixture of NCI-N87 cancer cells with fibroblasts at different ratios showed significant correlations with minimal variations." (PMID 31850215, 2019). "With respect to cancer progression, the expression of vimentin and snail is are characteristic of the epithelial-to-mesenchymal transition (EMT)." (PMID 31215499, 2019). "In cancer, vimentin is a driver of cancer progression and contributes to the invasive phenotype of metastatic cancer cells." (PMID 30894168, 2019). "Conversely, when the cells were exposed to the malignant fluid, the expression of E-cadherin was decreased, whereas the expression of vimentin was increased significantly in both types of cancer cells." (PMID 30609691, 2019). "Still, subsequent studies using cancer cells with additional genetic alterations revealed the requirement of vimentin in metastasis." (PMID 31126068, 2019). "In this review, we will discuss the functions of IF proteins in cancer, focusing on a subset of IFs that have been most widely studied in the context of cancer—keratins, vimentin, and nestin." (PMID 31126068, 2019).
cancer (continued). "Vimentin protein also plays a major role in cancer initiation and progression such as EMT, and metastasis." (PMID 31766246, 2019). "Our results also determine that AC mediated anti-cancer effects in CRC’s were associated with the decreased expression of EMT related β-catenin and vimentin genes." (PMID 31349708, 2019). "Ajoene inhibited the invasion and migration of both cancer cell lines which was found to be dependent on the presence of vimentin." (PMID 30894168, 2019). "Vimentin is widely accepted as a mesenchymal biomarker to promote EMT of various cancer cells, thereby promoting invasion and metastasis in vitro and in vivo." (PMID 31438963, 2019). "We further discovered that BECN1 interacted with Vimentin, which was implicated in epithelial–mesenchymal transition (EMT) and cancer cell migration." (PMID 31272261, 2019). "After 6 weeks, the mice were euthanized and inguinal lymph nodes were harvested for human vimentin IHC as a measure of lymph node colonization by cancer cells." (PMID 30674873, 2019). "Upregulation of mesenchymal markers, like vimentin, and loss of function of adherent junction protein E-cadherin are typical changes, indicating EMT of cancer cells." (PMID 31393941, 2019). "In agreement with the literature, vimentin overexpression was found to increase the migratory potential of both cancer cell lines up to 130%." (PMID 30894168, 2019). "Not only are several keratins present in the same tumors, but in certain cancer types, vimentin is co-expressed with keratins." (PMID 31126068, 2019). "Epithelial–mesenchymal transition (EMT) plays an important role in cancer cell invasion and metastasis, and E-cadherin and vimentin are critical regulators of EMT." (PMID 31404982, 2019). "Use of the human-specific V9 anti-vimentin antibody clearly distinguishes the presence of EMT in cancer cells from surrounding mouse stroma." (PMID 31234417, 2019). "In fact, tumors characterized by numerous vimentin-positive cancer cells are classified as highly undifferentiated/aggressive lesions." (PMID 31614564, 2019). "It’s widely accepted that as a mesenchymal marker, Vimentin promotes invasion and metastasis in various cancers." (PMID 31438963, 2019). "These molecular changes include alteration in Vimentin expression (a mesenchymal marker), which increases as the cancer progresses and the cells become more invasive." (PMID 31781476, 2019). "qPCR analyses revealed that the mesenchymal markers (i.e. SNAI1, SNAI2, ZEB1, ZEB2, CDH2, vimentin and fibronectin) expression was decreased in cancer EVs-exposed BRCA1-KO fibroblasts, while the expression of CDH1 was increased." (PMID 31200749, 2019). "The study also established that a selective inhibitor of Mnk1/2 strongly blocks migration of fibroblasts and cancer cells besides reducing the expression of vimentin, a marker of mesenchymal cells." (PMID 30832411, 2019). "Fumarate was previously reported to promote the expression of vimentin, an epithelial-to-mesenchymal transition marker, in cancer cells." (PMID 31729379, 2019). "In a study carried out by Satelli, it was shown that the increased invasive/migratory potential of cancer cells is related to VIM overexpression." (PMID 31294654, 2019). "Some studies have confirmed that E-cadherin and vimentin modulate cancer cell adhesion and prevent cancer cell metastasis." (PMID 30841634, 2019). "This interaction results in the disruption of the vimentin filament network and contributes to the anti-metastatic activity of ajoene in cancer cells." (PMID 30894168, 2019). "This protective effect was explained by the role of VIM in the regulation of cancer cell-platinum resistance." (PMID 31552188, 2019). "Expression of vimentin is regulated by the Vim gene regulating cancer cell migration and invasiveness." (PMID 31641356, 2019). "In this study we identify vimentin as a target that undergoes thiolysis exchange with ajoene in cancer cells." (PMID 30894168, 2019).